MYC (MYC proto-oncogene, bHLH transcription factor)
Diseases named in the same sentence as MYC in open-access papers (continued):
Sharing a sentence is not in itself a finding about the gene and the disease.
tumor (continued). "In this context, exogenous expression of c-MYC in the absence of circMIRO1 only partially recovered tumor growth in vivo, suggesting that regulation of c-MYC expression may be only one of many mechanisms circMIRO1 promotes tumor growth." (PMID 39128718, 2024). "Collectively, MYC functions differently in different types of tumor cells, and metabolic requirements differential within specific cancer types might dictate the outcome of glutamine metabolism regulated by MYC." (PMID 38218942, 2024). "In the absence of SMAD4, BMP4 promotes primary tumor growth that is accompanied by increased expression of genes associated with DNA replication, cell cycle, and MYC signalling pathways." (PMID 38689334, 2024). "Moreover, we observed elevated p-S121 NUDT1 levels in MYC(N) high tumor cells and tumor samples in comparison to those with low MYC(N) expression." (PMID 38493213, 2024). "Despite the prevailing view that most molecular interactions with MYC result from unproductive encounters, it is possible that a specific factor may retain MYC into a particular complex to effectively regulate gene transcription in tumor cells." (PMID 39615685, 2024). "Therefore, the role of the MYC-PVT1 regulatory axis is crucial, considering that many therapeutic strategies against neoplasia focus on MYC." (PMID 39123456, 2024). "In tumors with MYC overexpression, tumor cells become dependent on MYC." (PMID 38638876, 2024). "Moreover, consistent with our in vitro results, immunohistochemical staining of fresh tumor samples showed that the expression of MYC and ribosome biogenesis proteins were downregulated by BRQ monotherapy or combination with venetoclax." (PMID 38918775, 2024). "Additionally, MBII and MB0 are critical in tumor initiation, which induce tumorigenesis, aggravating the oncogenic effects of MYC." (PMID 37450923, 2024). "Interestingly, glutamine itself can also regulate the expression of c-MYC protein in some tumor cells." (PMID 38459595, 2024). "First, transformation of normal cells into tumor cells can occur via MYC gene overexpression." (PMID 39482742, 2024). "In addition, A80.2HCl treatment significantly inhibited both T24 and UMUC14 xenograft tumor growth in mice but exerted little effect on MYC-knockdown xenograft tumors." (PMID 38424044, 2024). "LCA histology and MYC amplification are used for high-risk tumor stratification in non-WNT/non-SHH MBs34." (PMID 39043693, 2024). "Furthermore, both Wnt/β-catenin and PD-L1/PD-1 inactivate CD8+ T-cell function by influencing the c-MYC gene during carcinogenesis and tumour formation, enabling tumour cells to evade the immune system." (PMID 39735605, 2024). "Additionally, AEG-1 demonstrated a correlation with angiogenesis, apoptosis, extracellular matrix-related genes, epithelial-mesenchymal transition markers, G2/M checkpoints, immune response, MYC markers, and tumor proliferation in HNSC." (PMID 39483471, 2024). "MYC activity is mainly described as an enhancer of tumor development." (PMID 38204280, 2024).
tumor (continued). "Our findings indicate that the MYC + epithelial subcluster shows greater anoikis resistance compared to other subclusters, and that anoikis resistance progressively increases across all subclusters as the tumor advances." (PMID 38802480, 2024). "Cumulatively, MYC systemically extends itself in creating an immunosuppressive environment by recruiting pro-tumoral macrophages, repelling anti-tumor immune cells, releasing cytokines, and modulating immune checkpoint molecules, by transcriptionally activating key gene targets." (PMID 38390324, 2024). "Additionally, the tumor is strongly positive for both MYC and BCL6, classifying it as double-hit lymphoma, or the double-expressor type, which is associated with an extremely poor prognosis and a median survival of 12-18 months." (PMID 39651017, 2024). "As both GS and GLS1 are transiently expressed in different tumor cell subcellular compartments, MYC can activate both reactions simultaneously in an individual cell; glutaminolysis occurs in mitochondria, whereas glutamine synthesis primarily takes place in the cytosol." (PMID 37450923, 2024). "Conversely, inhibiting MYC amplification in SCLC cell lines hampers tumor cell growth." (PMID 38892831, 2024). "This interaction suggests a coordinated regulatory mechanism in which p-STAT4 and CBP may synergistically influence expression of c-MYC and ultimately lead to tumour progression and docetaxel resistance." (PMID 38429845, 2024). "Moreover, MYC/MYCN amplifications can derive group 3/4 tumor cells away from the original GC/UBC lineage and exhibited worse outcome." (PMID 38355808, 2024). "However, unlike the binding between CREPT and RNAPII, our observations indicated that the interaction between CREPT and MYC is more likely to occur during the late S and G2/M phases of the cell cycle in both transformed MEFs and human tumor cells." (PMID 39615685, 2024). "Accumulating evidence suggests that MYC regulates a variety of oncogenic genes that trigger cancer cell proliferation, evasion, metabolic alteration, and even immune cell dysfunction in the tumor microenvironment." (PMID 39615685, 2024). "For IFNGR2, STAT1 and MYC, both sgRNA pools significantly increased the number of eGFP positive 2D3TCR/dCas9 cells (right), in line with their role as positive regulators of PD-L1 expression in tumor cells." (PMID 39497819, 2024). "In addition to the cellular response to hypoxia, TPX2 positively correlated with multiple carcinogenesis-related pathways, such as the PI3K/AKT/mTOR pathway, tumor proliferation signature, and MYC targets." (PMID 38833082, 2024). "Consistent with the results from the Foxo1Rictor double-KO studies, both c-MYC/FOXO1AAA and c-MYC/pT3-EF1α mice developed a high tumor burden and had to be euthanized by 6–9 weeks after injection, suggesting that activated FoxO1 did not improve the survival of c-MYC mice." (PMID 39325536, 2024). "Its phosphorylated form, p-ANXA2 (Tyr23), may promote tumor growth and metastasis through the MYC-HIF-1α-VEGF signaling axis." (PMID 39594718, 2024). "MYC activation is characteristic of various aggressive tumor types." (PMID 38390324, 2024). "Furthermore, IHC analysis of subcutaneous tumors indicated that NCAPG2 knockdown led to reduction in the level of c-MYC, following tumor shrinkage in vivo (Welch’s t-test P < 0.01)." (PMID 38166947, 2024). "Although the precise mechanism remains unclear, both in vitro and in vivo studies suggest that MYC amplification accelerates tumor growth, thereby shortening the survival of SCLC patients." (PMID 38892831, 2024). "Tumor cells with MYC overexpression show dysregulation of the cell cycle, which could make their proliferation especially sensitive to the inhibition of cyclin-dependent kinase (CDK), a key regulator of cell cycle progression." (PMID 38638876, 2024).
tumor (continued). "Finally, JHU083 caused a global shutdown in glutamine-utilizing metabolic pathways in tumor cells, leading to reduced HIF-1α, c-MYC phosphorylation, and induction of tumor cell apoptosis, all key antitumor features." (PMID 38701369, 2024). "MYC may control a multitude of cellular functions through regulation of nuclear transport of proteins and RNA, thus promoting tumor progression." (PMID 38302473, 2024). "As a proof-of-principle, we targeted one of the nuclear to cytoplasmic transport genes, XPO1, demonstrating its inhibition induced tumor cell death both in vitro and in vivo, in mouse and human MYC-driven cancer cell lines, in a transgenic mouse model of MYC-driven HCC, and in human HCC PDX." (PMID 38302473, 2024). "Furthermore, BRQ shows potential for clinical application, effectively reducing tumour growth and MYC expression in vitro and in vivo." (PMID 39766063, 2024). "In combination, there were further anti-MB effects on the tumor growth and MYC expression in mice." (PMID 38200580, 2024). "Both C/EBPδ and HIF-1α might thus contribute to the reduced suppression of MYC targets upon C/EBPδ induction under hypoxia and promote tumor cell survival in vivo." (PMID 39273396, 2024). "Besides, HIF1α and MYC are associated with increased oxidant stress and play important roles in the transition of EMT-like tumor cells to MET-like state, which is necessary for metastatic colonization." (PMID 38218942, 2024). "For example, there could be a greater impact on genes regulated by VDR related to angiogenesis, invasion, and metastasis (e.g., HIF1α and IL-8) compared with genes that influence tumor initiation (i.e., malignant transformation) (e.g. MYC and RB)." (PMID 39705237, 2024). "However, the expression of CD133/PROM1, OCT4/POU5F1, KLF4, and MYC occurred more frequently compared to EPCAM-negative tumor spots." (PMID 39456890, 2024). "This shows that MYC systemically extends itself in creating an immunosuppressive environment by recruiting pro-tumoral macrophages, repelling anti-tumor immune cells, releasing cytokines, and modulating immune checkpoint molecules, by transcriptionally activating key gene targets." (PMID 38390324, 2024). "Thus, MYC expression above physiologically permissible thresholds can induce tumor development or strongly accelerate tumorigenesis in multiple tissues." (PMID 39830506, 2024). "MYC amplification was found in 21% of the samples in a pan-cancer analysis of genomic and expression data of the TCGA dataset involving ~ 9000 samples covering 33 tumor types." (PMID 39031286, 2024). "Importantly, triptolide and Minnelide were both able to attenuate the growth of primary and metastatic lesions in various G3 MB mouse models, subsequently increased the survival of tumor-bearing mice, and they did so in a MYC-dependent manner." (PMID 38885332, 2024). "This enabled us to determine many previously unknown MYC-SL genes and genes with potential tumor suppressive properties." (PMID 38302473, 2024). "This demonstrates not only that SPT5 is an attractive candidate for targeting MYC-mediated oncogenic growth, but also suggests that inhibition of an essential process, such as transcription, could open a therapeutic window in tumor treatment." (PMID 37935464, 2024). "Our current information suggests that an mTOR-dependent enhancement of ATP production and HIF-1α levels may contribute to this LMP2A-dependent enhancement in MYC-driven tumor development and potentially the need to bypass additional oncogenic mutations." (PMID 38612754, 2024). "Besides MYC, a second TF, hypoxia-inducible factor-1α (HIF-1α), controls tumor cell glycolysis under oxygen deficient conditions." (PMID 37450923, 2024). "One paper identified GATAD2B to enhance tumor growth through direct interaction with MYC." (PMID 39696035, 2024).
tumor (continued). "The pronounced increase in nuclear puncta observed in our MYC E242-E261 mutant data may also contribute to genomic protection, potentially influencing the favorable selection processes in tumor growth." (PMID 39343006, 2024). "It has been shown that PNRC1 inhibits RAS- and MYC-driven tumor cell proliferation." (PMID 39046443, 2024). "Functional enrichment analysis (see Section 2) revealed that dysregulated circRNAs were enriched in cell proliferation pathways such as ‘Mitotic spindle’, ‘G2 M checkpoint’, and ‘MYC targets’, genome instability pathways such as ‘UV response’, and tumour signalling such as ‘TGF beta signalling’." (PMID 39428382, 2024). "Although MYCi975 could ablate CSCs with high MYC expression, the tumor cells with low MYC expression were able to proliferate and sustain the tumor bulk until they were worn out." (PMID 38169606, 2024). "Acetylsalicylic Acid can inhibit MYC (RPN1 interacting protein) levels in some tumor cells." (PMID 38431573, 2024). "Therefore, the acute and effective suppression of MYC expression and its downstream targets can be achieved by targeting the hyperactive transcription machinery in tumor cells." (PMID 38326887, 2024). "While summarizing these lncRNAs in CRC, we broadened our scope to other cancer models and the known lncRNAs involved, surprisingly, we observed that some MYC-related lncRNAs may have different functions in different tumor types." (PMID 39075086, 2024). "As MYC expression has been shown to correlate tumor response to triptolide treatment, we asked whether our L1000 data set–based predictions would align with this observation." (PMID 38885332, 2024). "Additionally, this cell cluster exhibits strong activity in the MYC target pathways V1 and V2, highlighting the potential pivotal role of MYC in driving the transcriptional programs of these tumour cells." (PMID 38958577, 2024). "Our results showed that compared to the control group, MZ-1 or doxycycline alone decreased the tumor size and consequently prolonged mouse survival; and that dual targeting of MYC and JUNB by MZ-1 and doxycycline, respectively, significantly enhanced their anti-MM activity." (PMID 39160158, 2024). "MYC, a well‐known oncogene, has been extensively studied in tumour research." (PMID 38506098, 2024). "One of the commonly expressed tumour genes in human cancer is MYC." (PMID 38637125, 2024). "We found a highly significant negative correlation between individual tumor scores in these bulk tumor tissue along a MYC–PRC axis, with PDS1 tumors displaying high-MYC–low-PRC target expression and PDS3 tumor displaying low-MYC–high-PRC target expression, and PDS2 tumors being intermediate." (PMID 38351382, 2024). "Thus, dual targeting of both HDAC and MYC pathways has the potential of inducing robust expression of ISGs, thus promoting tumor cell death mediated by viral mimicry." (PMID 39093942, 2024). "To address whether the interaction between CREPT and MYC plays a role in tumorigenesis, we examined colony formation and tumor growth using xenograft models." (PMID 39615685, 2024). "Importantly, Minnelide acted on MYC to reduce tumor growth and leptomeningeal spread, which resulted in improved survival of G3 MB animal models." (PMID 38885332, 2024). "Similarly, SIRT2 contributes to tumorigenesis by regulating KRAS acetylation and MYC stability, while influencing the inflammatory responses that shape the pro-tumor microenvironment." (PMID 39682281, 2024).
tumor (continued). "The cisplatin-resistant PDX model showed no response to cisplatin treatment, whereas MYCi975 alone or MYCi975 plus cisplatin significantly inhibited tumor growth in terms of volume and weight, suggesting that MYC inhibition overcame cisplatin resistance of HNSCC in vivo." (PMID 38169606, 2024). "For example, JQ1, a tert-butyl synthetic precursor of OTX015, is a prototype BET inhibitor (BETi), which competitively binds to the bromodomain and displaces BRD4 from super-enhancers for the MYC oncogene thus impeding tumor cell growth in various malignancies, including MM." (PMID 39160158, 2024). "Indeed, the key transcriptional regulator of the SCLC-A subtype, ASCL1, upregulates expression of SOX2, and this is important in both tumor establishment and MYC-dependent subtype regulation." (PMID 39456533, 2024). "Therefore, inhibition of the Wnt signalling pathway in cancer cells can disrupt PD-L1 expression by affecting MYC signalling, thereby enhancing the immune defence against tumours." (PMID 39735605, 2024). "Consistent to our hypothesis, MYC amplification promoted tumor development with low Ascl1 expression though in SCLC mouse models." (PMID 38233864, 2024). "In line with this, pG3myc MB showed a high fraction of tumor cell nuclei with accumulation of MYC." (PMID 39043693, 2024). "Finally, we treated MYC+CreERT2+ Vk22284 and Vk21153 tumor-bearing mice with tamoxifen for five consecutive days and monitored M-spike levels." (PMID 38714690, 2024). "These could also include synthetic lethal targets: here, any protein or signalling pathway that is essential for the survival of MYC-driven tumour cells can be targeted and many such targets are in clinical development." (PMID 38510176, 2024). "Tumor suppression of MYC-CaP-CR appears to be more complete in the immunocompetent mice, suggesting that immune stimulation could have contributed to tumor suppression in this model." (PMID 38546787, 2024). "Upon treatment with JQ1, a bromodomain and extraterminal domain (BET) inhibitor, MYCN, MYCNOT, and mrtl nearly vanish, coinciding with a notable increase in apoptosis levels in pediatric embryonal tumor cell lines that rely on MYC to maintain an undifferentiated phenotype." (PMID 39333489, 2024). "MYC overexpression downregulates antigen-presenting and costimulatory molecules on tumor cells, enabling them to avoid immune system recognition; hence, MYC overexpression disrupts physical interactions between T cells and cancerous/precancerous cells with negative consequences." (PMID 37450923, 2024). "The tumor was reported to have a BRCA1 germline mutation and a MYC amplification." (PMID 38566237, 2024). "Furthermore, when we compare the CMS2 tumours with the rest of the CMS tumours, we find the same association with specific biomarkers of WNT and MYC signalling." (PMID 38339195, 2024). "Knocking down either KLHL42 or MYC-sensitized tumor cells to CDK4/6i treatment." (PMID 38424044, 2024). "MYC promotes cell proliferation under conditions that would typically prove fatal for normal cells by manipulating glucose metabolism and eluding immunosurveillance by releasing metabolites within the tumor microenvironment (TME)." (PMID 38390324, 2024). "c-MYC is a tumor driving gene that was found overexpressed in numerous cancers including CRC." (PMID 37025163, 2023). "MYC is a proto-oncogene with crucial role in tumor initiation, progression, and maintenance." (PMID 37898690, 2023). "Indeed, we found that high TFB activates G2M checkpoints, E2F targets, MTORC1 signaling, and MYC targets, facilitating tumor occurrence and development." (PMID 37189078, 2023). "Besides, the tumor-derived exosome miR-105 makes CAFs appear in different metabolic patterns when faced with high or low nutrient levels, by activating MYC signaling." (PMID 37208722, 2023). "MYC therefore regulates glycosylation to enable tumor immune evasion." (PMID 36897988, 2023).